LPCAT2 (lysophosphatidylcholine acyltransferase 2)
Description:
Exhibits both acyltransferase and acetyltransferase activities. Catalyzes the conversion of lysophosphatidylcholine (1-acyl-sn-glycero-3-phosphocholine or LPC) into phosphatidylcholine (1,2-diacyl-sn-glycero-3-phosphocholine or PC). Catalyzes the conversion 1-acyl-sn-glycerol-3-phosphate (lysophosphatidic acid or LPA) into 1,2-diacyl-sn-glycerol-3-phosphate (phosphatidic acid or PA) by incorporating an acyl moiety at the sn-2 position of the glycerol backbone. Involved in platelet-activating factor (PAF) biosynthesis by catalyzing the conversion of the PAF precursor, 1-O-alkyl-sn-glycero-3-phosphocholine (lyso-PAF) into 1-O-alkyl-2-acetyl-sn-glycero-3-phosphocholine (PAF). Also converts lyso-PAF to 1-O-alkyl-2-acyl-sn-glycero-3-phosphocholine (PC), a major component of cell membranes and a PAF precursor (By similarity). Under resting conditions, acyltransferase activity is preferred (By similarity). Upon acute inflammatory stimulus, acetyltransferase activity is enhanced and PAF synthesis increases (By similarity). Involved in the regulation of lipid droplet number and size.
Synonyms: LysoPAFAT; AGPAT11; AYTL1; FLJ20481; LPLAT9
Tractability: Antibody: UniProt places it where antibodies can reach, with medium confidence; UniProt predicts a signal peptide or a membrane-spanning region; its Gene Ontology location is reachable by antibodies, with medium confidence. PROTAC: ubiquitination databases record sites on it; its protein half-life has been measured.
Gene: Protein-coding gene on chromosome 16 (55,508,994 to 55,586,666, forward strand). Ensembl gene ENSG00000087253.
Subcellular location: Endoplasmic reticulum membrane; Golgi apparatus membrane; Cell membrane; Lipid droplet
Subcellular location (Human Protein Atlas): Endoplasmic reticulum; Lipid droplets
Pathways (Reactome):
Metabolism: Acyl chain remodelling of PC
Gene Ontology:
Molecular function: 1-acylglycerol-3-phosphate O-acyltransferase activity; 1-acylglycerophosphocholine O-acyltransferase activity; 1-alkylglycerophosphocholine O-acetyltransferase activity; protein binding; 2-acylglycerol-3-phosphate O-acyltransferase activity; lysophosphatidic acid acyltransferase activity; plasmalogen synthase activity; 1-alkylglycerophosphocholine O-acyltransferase activity; acyltransferase activity; calcium ion binding
Biological process: phosphatidylcholine acyl-chain remodeling; membrane organization; platelet activating factor biosynthetic process; glycerophospholipid metabolic process; phospholipid metabolic process
Cellular component: endoplasmic reticulum; endoplasmic reticulum membrane; lipid droplet; Golgi membrane; Golgi stack; plasma membrane; membrane; organelle subcompartment
Genetic constraint (gnomAD): Loss-of-function variants: 38 observed, 41.92 expected, observed/expected ratio (o/e) 0.91, 90% interval 0.7 to 1.19. The upper end of that interval is the gene's LOEUF score, 1.19, which puts it in group 5 of 6, group 1 being the genes least tolerant of losing a copy. Missense variants: 481 observed, 525.94 expected, observed/expected ratio (o/e) 0.91, 90% interval 0.85 to 0.99. Synonymous variants: 218 observed, 197.98 expected, observed/expected ratio (o/e) 1.1, 90% interval 0.99 to 1.23.
Homologues: Orthologues: chimpanzee LPCAT2 (99% identical), macaque LPCAT2 (97% identical), dog LPCAT2 (90% identical), rabbit LPCAT2 (90% identical), pig LPCAT2 (90% identical), rat Lpcat2 (89% identical), mouse Lpcat2 (88% identical), guinea pig LPCAT2 (82% identical), tropical clawed frog lpcat2 (64% identical), zebrafish lpcat2 (58% identical), Drosophila melanogaster LPCAT (33% identical). Paralogues in human: LPCAT1 (42% identical), LPCAT4 (39% identical), GPAT4 (16% identical), GPAT3 (15% identical).
Diseases named in the same sentence as LPCAT2 in open-access papers:
LPCAT2 is named in the same sentence as 39 diseases in open-access papers, as found by Europe PMC text mining. Sharing a sentence is not in itself a finding about the gene and the disease. The quoted sentences say what the papers report.
colorectal cancer (25 papers, 2014 to 2026). A primary or metastatic malignant neoplasm that affects the colon or rectum. "In colorectal cancer, increased LPCAT2-mediated lipid droplet (LD) production has been linked to resistance against oxaliplatin and 5-fluorouracil." (PMID 37841917, 2023). "It has been previously reported that phosphatidylcholine synthesis in colorectal cancer is linked with the expression of lysophosphatidylcholine acyltransferase 2 (LPCAT2) in the lipid droplet (LD) accumulation of cancer cells." (PMID 36233276, 2022). "LPCAT2 controls the chemical resistance of colorectal cancer and may be associated with the dedifferentiation of thyroid cancer." (PMID 37240761, 2023). "For instance, lysophosphatidylcholine acyltransferase 2 (LPCAT2), an enzyme associated with lipid droplets, has been found to promote abnormal biosynthesis of phosphatidylcholine, leading to resistance to oxaliplatin and 5-fluorouracil in colorectal cancer." (PMID 37841917, 2023). "LPCAT-2-dependent lipid droplet accumulation in colorectal cancer causes calreticulin sequestration and prevents its exposure to the plasma membrane, thereby preventing DC maturation and subsequent CD8 T cell infiltration and immunogenic cell death under chemotherapy." (PMID 33530546, 2021). "LPCAT2-mediated lipid droplet production has been shown to confer resistance to 5-fluorouracil and oxaliplatin in colorectal cancer cells." (PMID 41145471, 2025). "A recent study on colorectal cancer found that the accumulation of lipid droplets, which is dependent on lysophosphatidylcholine acyltransferase 2 (LPCAT-2), prevented calreticulin from being exposed to the plasma membrane." (PMID 38765144, 2024). "Reportedly, chemoresistance of colorectal cancer cells was produced by LPCAT2-mediated lipid droplet formation, which was also aided by prothymosin α, and metastasis-associated in colon cancer through SREBP-1- and FASN-mediated lipogenesis respectively." (PMID 37584712, 2023). "The production of lipid droplets via the LPCAT2 pathway promoted chemoresistance in colorectal cancer." (PMID 37294538, 2023). "LPCAT2-mediated LD production is known to contribute to chemotherapy resistance in colorectal cancer." (PMID 33530546, 2021). "Abnormal biosynthesis of phosphatidylcholine, facilitated by the lipid droplet-bound enzyme lysoRS acyltransferase 2 (LPCAT2) has been found to contribute to resistance to oxaliplatin in colorectal cancer." (PMID 34944789, 2021). "For instance, a study of a colorectal cancer mouse model specified that LPCAT2 (LPC acyltransferase 2) contributed to LD accumulation, thus resulting in chemotherapy resistance." (PMID 32543783, 2020). "Reportedly, chemoresistance of colorectal cancer cells was produced by LPCAT2-mediated lipid droplet formation, which was also aided by prothymosin α,25 and metastasis-associated in colon cancer 126 through SREBP-1- and FASN-mediated and lipogenesis respectively." (PMID 38241178, 2024). "Importantly, LPCAT2 mediated lipid droplet production has been shown to promote resistance to chemotherapy in colorectal cancer." (PMID 35774129, 2022). "Likewise, in colorectal cancer, the production of LDs mediated by lysophosphatidylcholine acyltransferase 2 (LPCAT2) was correlated with resistance to 5-fluorouracil and oxaliplatin both in vitro and in vivo." (PMID 35164256, 2022). "Of note is that LPCAT2, discussed earlier in phospholipid remodelling, may also promote lipid droplet accumulation, as its expression has been shown to correlate with their content in colorectal cancer cells." (PMID 40759959, 2025). "Thus, targeting LPCAT2-mediated intracellular LD formation may be a therapeutic approach to restore chemotherapy sensitivity in colorectal cancer." (PMID 33530546, 2021). "In colorectal cancer, LPCAT2 regulates the acetylation of Protein Arginine Methyltransferase 1 (PRMT1) at the K145 site, preventing the cytoplasmic transport of PRMT1 in colorectal cancer cells." (PMID 41513612, 2026).
colorectal cancer (continued). "Other studies revealed that increased expression of lysophosphatidylcholine acyltransferase 2 (LPCAT2), i.e., a key enzyme in phosphatidylcholine synthesis, correlated with an increased LD content and was shown to co-localize with LDs in colorectal cancer." (PMID 30767150, 2019). "LPCAT2 and LPCAT4 contributes to initiation and chemoresistance in colorectal cancer." (PMID 37294538, 2023). "Likewise, reducing the content of LDs by silencing lysophosphatidylcholine acyltransferase 2 sensitized colorectal cancer HT29 cells and SW620 cells to 5-fluorouracil and oxaliplatin, and similar results were also observed in a colorectal cancer xenograft mouse model." (PMID 38500157, 2024).
colon carcinoma (7 papers, 2020 to 2025). "To explore the dynamic changes in LPCAT2 expression during colon cancer progression, we established colitis-associated colon cancer (CAC) mouse model by challenging C57BL/6 mice with intraperitoneal injection of AOM and water-fed DSS." (PMID 38605214, 2024). "To further validate the LPCAT2 expression pattern in CRC, we detected LPCAT2 protein levels in 50 colon cancer tissues." (PMID 38605214, 2024). "The LPCAT2 expression in left-sided colon cancer tissues was higher than that in right-sided tissues." (PMID 38605214, 2024). "Furthermore, in LPCAT2 knockout mice (LPCAT2−/−) colon cancer model, we found that LPCAT2−/− mice exhibited more severe lesions, while PRMT1 or SLC7A11 inhibitors delayed the progression." (PMID 38605214, 2024). "In subsequent in vivo experiments using a colon cancer mouse model, the administration of LPCAT2 or LD biogenesis inhibitors resulted in tumor regression and increased survival, indicating the significant improvement of LPCAT2-mediated drug resistance." (PMID 37841917, 2023). "The LPCAT2 expression levels were positively correlated with aggressive behavior in prostate cancer and were significantly upregulated in cervical, breast, and colon cancer tissues, suggesting a role in the progression of these tumors." (PMID 33392068, 2020).
prostate carcinoma (7 papers, 2014 to 2022). A carcinoma that arises from epithelial cells of the prostate gland. "In summary, we have identified CXCL14, ITGAX and, LPCAT2 as novel susceptibility genes for aggressive prostate cancer development." (PMID 25411967, 2014). "Second, three of these five genes (CXCL14, ITGAX, and LPCAT2) harbored polymorphisms associated with aggressive disease development in a human GWAS cohort consisting of 1,172 prostate cancer patients." (PMID 25411967, 2014). "LPCAT2 was recently associated with prostate cancer aggressiveness." (PMID 29358673, 2018). "Increased expression of LPCAT2 is associated with poor prognosis of PDAC patients and positively correlated with aggressive prostate cancer." (PMID 34650983, 2021). "This approach, which is novel to the field of prostate cancer to the best of our knowledge, facilitated the identification of three novel aggressive prostate cancer susceptibility genes: CXCL14, ITGAX, and LPCAT2." (PMID 25411967, 2014). "The expression level of LPCAT2 is positively correlated with aggressive prostate cancer." (PMID 35774129, 2022). "In addition, LPCAT2 is expressed in aggressive prostate cancer." (PMID 33854590, 2021).
cervical carcinoma (4 papers, 2014 to 2020). A carcinoma arising from either the exocervical squamous epithelium or the endocervical glandular epithelium. "In the current study, we showed a significant positive correlation between EGFR and PAFR, and between EGFR and LPCAT2 in 306 cervical cancer samples deposited in TCGA database." (PMID 33392068, 2020). "It was observed a strong positive correlation between the expression of EGFR × PAFR and EGFR × LPCAT2 in 306 cervical cancer samples." (PMID 33392068, 2020). "The prognostic impact of LPCAT2 and cPLA2 must be confirmed in other cohorts of cervical cancer patients since the increased expression of these genes was observed in a small number of cases (8/304 and 9/304, respectively)." (PMID 33392068, 2020). "For example, higher levels of expression of LPCAT2 are observed in a diverse range of tumors, notably breast and cervical carcinomas." (PMID 25411967, 2014). "Indeed, EGFR activation upregulated the expression of PAFR and LPCAT2 in cervical cancer cells through a MAPK-dependent mechanism." (PMID 33392068, 2020). "In the current study, strong positive correlations between EGFR × PAFR, and EGFR × LPCAT2 in cervical cancer samples were shown, which led to the hypothesis that EGFR can regulate the expression of these genes involved in the biosynthesis and signaling of PAF." (PMID 33392068, 2020). "Taken together, our data suggest that EGFR, LPCAT2, and PAFR emerge as novel targets for cervical cancer therapy." (PMID 33392068, 2020). "Collectively, we proposed that EGFR, LPCAT2, and PAFR emerge as novel targets for cervical cancer therapy." (PMID 33392068, 2020). "Herein, we identified EGFR, LPCAT2, and PAFR as targets for cervical cancer therapy, using TCGA-based in silico analyzes." (PMID 33392068, 2020). "Agarwal and Garg reported the AGPAT activity of AGPAT11/LPCAT2 and increased expression of AGPAT11 in breast cancer and cervical cancer tissues." (PMID 25415055, 2014). "Our results revealed that the LPCAT2 upregulation, but not PAFR, has negative prognostic value in cervical cancer patients." (PMID 33392068, 2020). "However, the upregulation of LPCAT2 (P = 0.0239), the same enzyme that positively correlates with the expression of EGFR, showed negative prognostic value for cervical cancer patients, as well as cPLA2 (P = 0.0052)." (PMID 33392068, 2020).
allergic disease (3 papers, 2016 to 2022). An immune response that occurs following re-exposure to an innocuous antigen, and that requires the presence of existing antibodies against that antigen. "For example, 4 genes of C2CD2, HLA-DRB6, LPCAT2, and HLA-DQB1 were associated with TB risk, and RUNX showed association with asthma or allergic disease risk." (PMID 33051402, 2020).
breast carcinoma (2 papers, 2014 to 2020). "Furthermore, all three variants linked to rs17301608 are reported expression quantitative trait loci (eQTLs) for LPCAT2 (lysophosphatidylcholine acyltransferase 2), which was previously associated with the progression of breast cancer, ovarian cancer and CRC in human tissue and in cell lines." (PMID 32751332, 2020).
Obesity (2 papers, 2014 to 2017). Accumulation of substantial excess body fat. "Although it is possible that inhibition of LPCAT2 may promote obesity, our compound may be a valuable reagent to investigate the role of LPCAT2 in obesity in vivo." (PMID 24850807, 2014).
pancreatic cancer (2 papers, 2021 to 2023). "The mRNA level of LPCAT2 was significantly upregulated in pancreatic cancer tissues compared with normal tissues." (PMID 37240761, 2023). "It has been reported that LPCAT2 is a target of miR-148a-5p and thus may be a prognostic gene for pancreatic cancer." (PMID 37240761, 2023). "We analyzed the mRNA expression levels of the MBOAT2/CDA/LPCAT2/B4GALT5 genes in PACA patient samples and pancreatic cancer cells." (PMID 37240761, 2023). "It is proposed that MBOAT2, CDA, LPCAT2 and B4GALT5 expression may promote the onset and progression of pancreatic cancer." (PMID 37240761, 2023). "The mRNA levels of MBOAT2, CDA, LPCAT2 and B4GALT5 were significantly higher in PACA cells than in normal human pancreatic duct epithelial cells, implying that the high expression levels of these four genes may promote the development and progression of pancreatic cancer." (PMID 37240761, 2023).
Sepsis (2 papers, 2020 to 2025). Sepsis is defined as life-threatening organ dysfunction caused by a dysregulated host response to infection. "Our data thus suggest a novel mechanism for the regulation of inflammatory gene expression in response to bacterial stimuli and highlight LPCAT2 as a potential therapeutic target for development of anti-inflammatory and anti-sepsis therapies." (PMID 32587324, 2020). "LPCAT2 may thus be a novel regulator of inflammation in innate immune cells and highlights LPCAT2 as a potential novel target in the development of new therapies for conditions with unregulated inflammatory responses such as sepsis." (PMID 32587324, 2020). "In sepsis-induced acute lung injury (SI-ALI), PDK4 hyperactivation drives excessive lactate production in epithelial cells, triggering AARS1/HDAC9-mediated LPCAT2 lactylation." (PMID 41057687, 2025).
allergic rhinitis (1 paper, 2023). Inflammation of the nasal mucous membranes caused by an IgE-mediated response to external allergens. "The methylation of LPCAT2 is associated with allergic rhinitis." (PMID 37240761, 2023).
Alzheimer disease (1 paper, 2025). A progressive, neurodegenerative disease characterized by loss of function and death of nerve cells in several areas of the brain leading to loss of cognitive function such as memory and language. "To explore potential causal relationships beyond observed correlations, we applied multiple MR approaches to assess whether genetic variants of LPCAT2 contribute to pain susceptibility and Alzheimer's disease risk." (PMID 40959955, 2025).
cognitive decline (1 paper, 2025). "We also validated these findings in an independent ethnic cohort, which confirmed a significant association between LPCAT2 SNPs, pain susceptibility, and cognitive decline in the same subpopulation, enhancing our understanding of AD in underrepresented populations." (PMID 40959955, 2025). "Future research should investigate the interplay between LPCAT2 genetic variants, expression levels, and inflammation, as well as their interactions with other genetic and environmental factors, to provide deeper insights into their role in cognitive decline." (PMID 40959955, 2025). "Moreover, we uncover a genotype‐ and sex‐specific relationship between LPCAT2 expression, cognitive decline, and pain susceptibility, underscoring the importance of considering both APOE genetic background and sex in AD pathophysiology." (PMID 40959955, 2025).
colibacillosis (1 paper, 2017). "We next compared the expression of acute pro-inflammatory mediators with PAFR and LPCAT2 expression in chicken lungs and liver, two organs where typical colibacillosis lesions are known to develop." (PMID 29326957, 2017). "In addition, PAF contributes to intracellular bacterial killing and EC dysfunction, two phenomena that may be correlated with the overexpression of PAFR and LPCAT2 in organs of chickens presenting colibacillosis." (PMID 29326957, 2017). "Both PAFR and LPCAT2 genes are overexpressed in chicken macrophages and chAEC upon LPS stimulation in vitro, which suggests that at least these cell types may be involved in the response to colibacillosis in vivo." (PMID 29326957, 2017).
esophageal cancer (1 paper, 2020). A primary or metastatic malignant neoplasm involving the esophagus. "The in vitro results showed that angustoline activated the expressions of LKB1 and AMPK and subsequently inhibited the levels of ELAVL1 and LPCAT2, which elucidated the anti-tumor mechanism of angustoline in esophageal cancer cell model." (PMID 32733803, 2020). "Additionally, the effects of angustoline on viability, migration and invasion of esophageal cancer cells (KYSE450) were evaluated, as well as the regulation of angustoline in LKB1/AMPK/ELAVL1/LPCAT2 pathway in KYSE450 tumor bearing mice was investigated." (PMID 32733803, 2020). "Here, for the first time, we had used siRNA fragments to provide a mechanism that linked ELAVL1 with phospholipid remodeling, proving ELAVL1 was involved in the overexpression of LPCAT2, which further catalyzed the conversion of LPC (16:0) to PC (16:0/18:1) in esophageal cancer cells." (PMID 32733803, 2020).